CXCL5 (C-X-C motif chemokine ligand 5)
Diseases named in the same sentence as CXCL5 in open-access papers (continued):
Sharing a sentence is not in itself a finding about the gene and the disease.
infection (continued). "A possible explanation is that Il22−/− showed a decrease in Cxcr2 expression after the peripheral infection had established (day 4 p.i.), and Il22−/− were also defective in brain Cxcl1 and Cxcl5 expression." (PMID 22952908, 2012). "For example, genes that encode for CXC-chemokines such as CXCL1 (Gro-α), CXCL5 (Ena-78) and CXCL9 (MIG) were significantly induced at D12 and were induced to higher levels on D15 and D21 post infection." (PMID 21249199, 2011). "Proinflammatory cytokines CXCL8 and CXCL5 are chemoattractants for neutophils, IL-1α and IL-1β are important proinflammatory cytokines and would be expected to be increased early in infection." (PMID 22331987, 2010). "A time-dependent increase of the number of Cxcl-2+ and Cxcl-5+ epithelial cells was detected after infection with wt Listeria." (PMID 21124989, 2010). "Concomitantly, genes involved in inflammatory and interferon-related responses, including IFN-γ, IL-12b, STAT1, STAT3, IL-6, TNF-α, CXCL9, CXCL10, and CXCL5, were significantly upregulated, indicating a strong pro-inflammatory environment during peak infection." (PMID 40630939, 2025). "Synovial CXCL5 over-expression was a universal hallmark of both active and dormant infection, whereas matched plasma profiles showed no discriminatory power for all immuno-oncology mediators tested." (PMID 41387890, 2025). "Various chemokines (small proteins that guide white blood cells to sites of infection, injury, or inflammation) in this pathway, such as Cxcl1, Cxcl2, Cxcl3, and Cxcl5 and Ccl20, showed significant differences in expression levels between the LV149-L and the DSS group." (PMID 39845056, 2024). "IL17, CXCL1, and CXCL5, which were elevated in dormant infections, are known signals for neutrophil attraction, yet we observe a reduction in signaling related to neutrophil trap formation during a dormant infection when evaluating KEGG pathways." (PMID 39563367, 2024). "Therefore, to assess the role of CXCL1, CXCL2, CXCL3, and CXCL5 in neutrophil trafficking during infection with C. violaceum, we used a CXCR2 inhibitor." (PMID 38352492, 2024). "The IL-6 family cytokine, oncostatin-M (OSM), also enhances the expression of CXCL5 and neutrophil influx into the lungs after infection with E. coli, likely as a result of OSM-specific STAT3 (signal transduction and activator of transcription 3) activation in lung epithelial cells." (PMID 36829255, 2023). "Cxcl1 and Cxcl5 production were induced in epithelial cells following chronic H. felis infection, while Cxcl2 and Cxcl3 production was induced in epithelial, myeloid, and T cell subsets following infection." (PMID 37744359, 2023). "Together, these data suggested that reconstitution of WT mice with the hematopoietic compartment of CXCL5-/- mice markedly decreased the levels of CXCL5 in infected lungs post infection, while reconstitution of CXCL5-/- mice with the hematopoietic compartment of WT mice resulted in CXCL5 production." (PMID 34868067, 2021). "Instead, bronchial airway epithelial cells were found to modulate host susceptibility to infection mediated through rhythmic glucocorticoid signaling, which drove oscillations in Cxcl5 expression from the epithelium, and thus differences in recruitment of neutrophils to the site of infection." (PMID 34512600, 2021). "Moreover, CXCL5-/-(WT BM) mice regained expression of CXCL5 post infection, and the dynamic change was similar to that in WT (WT BM) mice." (PMID 34868067, 2021). "CXCL5 is produced by lung tissue cells after infection based on data from chimeric mice, and it may be expressed by the alveolar type II epithelial cells." (PMID 34868067, 2021). "Furthermore, within the first 48 h of infection, the production of CXCL5, CCL3, CCL5, and, to a lesser extent, GM-CSF, was reduced." (PMID 33670363, 2021).
infection (continued). "In addition, increased B cell recruitment and accumulation in the infected lungs of CXCL5-/- mice also contributed to increased iBALT formation during the late infection and recovery stages." (PMID 34868067, 2021). "In addition, CXCL1, CXCL2, and CXCL5 suppress excess CXCL13 expression in macrophages via the CXCR2 axis during the early infection stage." (PMID 34868067, 2021). "to enhance pulmonary CXCL5 levels at the late infection stage." (PMID 34868067, 2021). "Notably, the mRNA levels of Tnf, Il6, Il1b, Cxcl10, and Cxcl5 were significantly increased and that of Il10 decreased in lung tissue from Ppara-/- mice, compared with Ppara+/+ mice, during Mabc infection." (PMID 32155958, 2020). "CXCL5 is secreted by endothelial cells in response to infection to recruit neutrophils." (PMID 33224151, 2020). "Additionally, closer examination of the leading-edge genes of significant chemokine gene sets shows significant representation of neutrophil chemokines (Cxcl5, Ccl4 and Cxcl1), suggesting strong phase:infection interaction effect." (PMID 30134832, 2018). "Compared to IL17A, IL17F was found to be a more potent inducer of CXCL5, a known neutrophil recruiter, indicating that F. hepatica may avoid excessive neutrophil recruitment during infection by suppressing the IL17F/CXCL5 axis." (PMID 27661612, 2016). "Interestingly, both pre-infection and post-infection treatment with curcumin not only inhibited NTHi-induced CXCL5 up-regulation but also suppressed PMN infiltration into the middle ear in a mouse model of OM." (PMID 27538525, 2016). "RANTES, MIF, MCP3 and CXCL5, showed increased transcription during the infection." (PMID 22331987, 2010). "Flow cytometric analysis of infected lung tissue showed a nearly complete absence of neutrophil influx during the early infection phase (10 dpi) which can be linked to the downregulation of Cxcl5 and lack of Cxcl1 and Cxcl2 upregulation responsible for neutrophil chemotaxis during inflammation." (PMID 36400767, 2022). "Similarly, chemokines (e.g. CXCL1, CXCL2, and CXCL5) that play a pivotal role in neutrophil recruitment to sites of infection and injury were induced 2–3 orders of magnitude, whereas CXCL12/SDF‐1 and adhesion G‐protein coupled receptor F5 (ADGRF5, GPR116) expression was unaffected." (PMID 36151614, 2022). "MRNA levels of genes encoding for chemokines (CXCL1 and CXCL5), cytokines (IL-10, IL-15 and IL-32), pattern recognition receptors (TLR1) and innate signaling molecules like IRAK3 and TRAF6, were all increased after MVA-C infection in comparison with MVA-WT-infected cells." (PMID 22536391, 2012). "The characteristic gene expression of dormant infection suggested the activation of interleukin (IL)-17 and tumor necrosis factor (TNF) pathways that drive synovial CXCL5 expression, which should stimulate neutrophil recruitment." (PMID 41387890, 2025). "In summary, CXCL6, CXCL5, and CCL20 chemokines are important for the mechanism of immune signaling during infections, playing a fundamental role in recruiting immune cells to the site of infection and enhancing the local immune response." (PMID 38474048, 2024). "Our data show that JCPyV-infected choroid plexus epithelial cells at 7 days post-infection, which represents two full viral life cycles, secrete a signature of proinflammatory chemokines, including CXCL8, CXCL5, CXCL6, and CCL2." (PMID 38874395, 2024). "Our results show that CC chemokine receptors and their ligands, which are necessary for neutrophil mobilization and recruitment to the lungs during infection, are down regulated in human CHIP carriers (e.g., CXCL1, CXCL5) and mice (e.g., CCR2, lung CCL2)." (PMID 38573824, 2024). "IL-17A promotes CXCL5, which has a similar effect to CXCL6, and attracts neutrophils, eosinophils, and T cells to the site of infection, enhancing the local immune response." (PMID 38474048, 2024).
infection (continued). "Dormant infections display M1 polarization as well as a local increase in CXCL13 and CXCL5, along with depleted IL7 within synovial fluid, strongly suggesting chronic inflammation." (PMID 39563367, 2024). "Infection of BMDCs with EBs opsonized with male IgG enhanced expression of chemokines CXCL1, CXCL2, CXCL5 and pro‐inflammatory cytokines TNF, IL1β and IFNγ compared to uninfected or non‐opsonized controls." (PMID 38441219, 2023). "ELR-type chemokines activated by cp strain infection included CXCL1, CXCL3, CXCL5, CXCL8, and CXCL15." (PMID 35746747, 2022). "Our findings demonstrated decreased expression and secretion of IL8, IL6 and TNFα, while CXCL5, PAI-1 and IFNα remained unaffected even 12 hours post-infection." (PMID 36389723, 2022). "CXCL5, known as LIX (LPS-induced CXC chemokine in mice), can activate neutrophils and attract them into tissues during inflammation and infection via its receptor, CXCR2." (PMID 35743888, 2022). "PAK elicited high levels of CXCL1, CXCL5, and CCL20 in BAL fluid (BALF) at 6 hours post-infection, with lower concentrations at 24 hours." (PMID 33793661, 2021). "Multiple factors contribute to neutrophil recruitment from the circulation to the site of infection, including proinflammatory cytokines (such as IL-1α, IL-1β, TNF-α, and IL-6) and Cxcr2 chemokines (such as Cxcl1, Cxcl2, Cxcl5, and Cxcl8)." (PMID 34011393, 2021). "Functional cytokine assays on sorted monocyte populations show that the infection-distinguishing monocytes secrete high levels of chemokines, such as CCL2 and CXCL5." (PMID 33273621, 2020). "In previous studies, our group has shown a significant increase of CXCL5 in lung and spleen of BALB/c mice after 1d of the infection with Leptospira." (PMID 30616505, 2019). "Infected, solvent-treated mice showed an infection-time-dependent increase in CXCL1, CXCL2 and CXCL5." (PMID 30382866, 2018). "Chemokine expression analysis revealed that T3SS mutant induced lower mRNA levels of CXCL1, CXCL2, CXCL5, CXCL10 and CCL20 than the wild-type strain at 16 h post-infection." (PMID 30070169, 2018). "Then, expression of TFF1 is gradually silenced when the infection becomes chronic and IFN-γ, CXCL5, and CXCL15 reach higher levels." (PMID 29085807, 2017). "Our results demonstrate that TFF1 is up-regulated in the acute phase of infection together with IL-1β and IL-6, while is down-regulated in the chronic phase of infection (after 42 days) when IFN-γ, CXCL5, and CXCL15 increase." (PMID 29085807, 2017). "Since CXCL5 is a neutrophil chemoattractant, we further evaluated the effect of curcumin on PMN recruitment in response to NTHi infection in a mouse model of OM." (PMID 27538525, 2016). "Infection activates a broad chemokine response to infection, including CXC (CXCL1, CXCL5, CXCL8, CXCL9, and CXCL10) and CC chemokines (CCL2, CCL3, and CCL5)." (PMID 26927188, 2016). "Curcumin treatment’s efficacy in inhibiting CXCL5 expression and PMN recruitment post-NTHi infection is of particular clinical significance." (PMID 27538525, 2016). "To further explore the role of IL-17 in host defense against S. aureus intramammary infection, we focused on neutrophil-recruiting chemokines that are the key target genes of IL-17, such as CXCL1, CXCL2 and CXCL5." (PMID 26230498, 2015). "A nine-analyte synovial panel consisting of PDGF-B, CXCL5, CXCL11, MCP-2 (CCL8), ANGPT1, TIE2, EGF, NOS3, and Gal-1 distinguished dormant infection from truly aseptic cases with 100% specificity and positive predictive value (sensitivity 22%, negative predictive value 74%)." (PMID 41387890, 2025). "The persistent overexpression of CXCL5 in the dormant state is striking, given the lack of neutrophil recruitment in joint replacements with a dormant infection, suggesting a disconnect between chemokine signaling and effector cell response." (PMID 41387890, 2025).
infection (continued). "Interestingly, we found CXCL5 was elevated in the lungs and BALF of A/J mice at all infection time points as well as in the BALF of uninfected A/J mice." (PMID 39823516, 2025). "Namely, CD5, CD8A, CD6 and CD244, C-C and C-X-C motif chemokines (CXCL5 CXCL6, MCP-4, and CCL20), as well as CD40, PDL-1, CUB domain-containing protein 1 (CDCP1) and interleukin-12B (IL-12B) were elevated in the late infection group compared to the unexposed group." (PMID 41510260, 2025). "Moreover, infection with SFV/IFNγ specifically inhibited GM-CSF, CCL20 and CXCL5 compared to the SFV group (p < 0.0001)." (PMID 40547518, 2025). "Chemokine measurement 6 hours post bacterial infection showed similar trends in some cytokines, but also highlighted the importance of cytokine kinetics within infection, as multiple chemokines were altered only at early time points, including CCL17, CCL22, IL-6, and CXCL5." (PMID 39178311, 2024). "However, at 30 days post-infection, TNF-α, IL-6, KC, CCL3, CCL2, CCL20, CXCL11, CCL11), CCL27, CXCL5, CXCL12 and CCL5 were all significantly higher in the BAL fluid of Duox1 KO compared to WT mice." (PMID 36936954, 2023). "However, CLEC2.Fc efficiently inhibited the expression of proinflammatory cytokines (IL‐6, TNF‐α, IFN‐γ, and IL‐10) and chemokines (CXCL1, CXCL2, CXCL5, CCL2, IP‐10) at day 3 and day 5 post‐infection (blue columns)." (PMID 37211986, 2023). "Furthermore, Dnmt3bfl/flSpCcre and control mice showed similar CXCL5, CCL20, IL-1β and TNF-α BALF levels upon infection with PAK." (PMID 33793661, 2021). "CXCL1, IL-8, and CXCL5 activate the CXCR2 receptor, the function of which is to recruit neutrophils to the site of inflammation where they play a central role in first-line defences against infection." (PMID 33780519, 2021). "Moreover, at 24 hours after infection, CXCL1 and CXCL5 concentrations in BALF were similar in both mouse strains." (PMID 33793661, 2021). "Furthermore, upon infection the bronchoalveolar and thoracic cavity lavage of S100A8/A9-/- mice showed increased concentrations of CXCL-1, CXCL-2, CXCL-5, as well as elastase in comparison to the WT controls." (PMID 32107497, 2020). "We report a strong induction of numerous pro-inflammatory cytokines, chemokines and AMPs such as CXCL1, CXCL2, CXCL5, CXCL8, CCL20, TNFα, TSLP, IL-23α, IL-32, IL-6, hBD2 and S100A7 during the infection of monolayered primary keratinocytes and reconstructed epidermis with the wild-type PAK strain." (PMID 30070169, 2018). "In particular, CCL2, CXCL5, and CXCL10 had increased levels early after wounding and infection." (PMID 30138446, 2018). "Independent of the genotype, infection with H. felis, resulted in downregulation of several genes, such as CXCL5 and TNFRSF13c (infected versus uninfected mice)." (PMID 26966907, 2016). "The molecules that depicted significant increases in those mAb treated-mice at 96 h after infection were CXCL1 (KC), CCL2 (MCP-1), CCL3 (MIP-1α), CCL4 (MIP-1β), CXCL2 (MIP-2), CXCL5 (LIX), IL-1α, IL-6, G-CSF, M-CSF, and TNF-α (for all, P < 0.01) and IL-1β, IL-15, IL-10, and LIF (for all, P < 0.05)." (PMID 27642235, 2016). "A significant time-dependent increase in Cxcl2 and Cxcl5 mRNA expression was measured after infection by WT or the complemented ΔinvC pinvC but not SPI1-deficient non-invasive Salmonella." (PMID 25210785, 2014). "For example, genes encoding several innate immune receptors and chemokines (such as TLR4, CD83, CCL2, CXCR4, CXCL5, IL1A and IL8)—several of which participate in the initiation of a T cell response during infection —showed increased relative expression in the BTB animal group." (PMID 22182502, 2011). "Expression of the chemokine Cxcl5 was impaired in the absence of either IL-1R or IL-17RA signaling, suggesting a role in both activation and maintenance of the neutrophil population during infection." (PMID 42085507, 2026).
infection (continued). "Following infection with K. pneumoniae, ablation of IL-17RA (interleukin-17 receptor A) in SCGB1A1 (secretoglobin family 1A member 1) expressing club cells significantly reduces CXCL5 levels, leading to reduced neutrophil recruitment and increased bacterial burden." (PMID 36829255, 2023). "Moreover, the secretion of neutrophil chemoattractants, CXCL1 and CXCL5, were significantly induced after 6- and 10-weeks post-infection in the absence of Lyl1." (PMID 36119114, 2022). "However, following infection, obese mice had increased circulating levels of B cell activating factor (BAFF, p = 0.0070), CCL5 (p = 0.0118), CCL17 (p = 0.0118), Chitinase-3-like 1 (p = 0.0118), CXCL5 (p = 0.0118), and IFN-alpha (p = 0.0118)." (PMID 32854687, 2020). "To identify mechanistic bases for the different numbers of neutrophils at the site of infection, we measured the main chemokine factors for neutrophil attraction, including the CCR1 ligands CCL3, CCL4, and CCL5 and the CXCR2 ligands MIP-2/CXCL-2, KC/CXCL-1, and CXCL5." (PMID 32424099, 2020). "We still do not understand how GDF15 negatively regulates CXCL5-mediated neutrophil recruitment to the site of infection, but previous reports have shown that GDF15 regulates neutrophil arrest and platelet aggregation under flow conditions by modulating the affinity of integrins." (PMID 32424099, 2020). "For example, infection of human embryonic neural progenitor cells with JCPyV resulted in significant upregulation of the cytokines/chemokines such as CCL5/RANTES, GRO, CXCL1/GROα, CXCL16, CXCL8/IL-8, CXCL5/ENA78, and CXCL10/IP-10 and the chemokine receptor CXCR2." (PMID 31408949, 2019). "We observed secretion of several chemokines in response to T. cruzi infection (CCL2, CXCL5 and CXCL10), which indicate that despite the lack of inflammatory cytokines, the macrophages are not completely immunologically unresponsive to infection." (PMID 31841511, 2019). "MCP3 and CXCL5 showed increases only late in the infection process, while CXCL8 (IL-8) showed increased transcription early in the infection then decayed to noninfected levels." (PMID 22331987, 2010). "The expression of CXCL3, CXCL5, and CXCL9 during A. baumannii infection has not previously been quantified, and the role that these effectors play in the outcome of infection is unknown." (PMID 36054235, 2022). "Interestingly, IL-6, IP-10, CXCL5, and MIP1-β levels were higher 12 weeks post infection in groups receiving no treatment, whereas all other time points were similar between each of the three groups (data not shown)." (PMID 29795025, 2018). "Vascular sequestration during a time of local neutrophil depletion helps explain the increased CXCL5, CXCL11, and MCP-2 levels, lack of systemic acute phase reactant expression, and continued monocyte and T-cell activity previously shown to be indicative of dormant infection." (PMID 41387890, 2025). "Co-stimulation of SARS-CoV-2 S protein with the TLR2 ligand PAM3csk4, increased significantly the expression of the inflammatory mediators CXCL5, PAI-1 and IFNα at 12 hours following infection, but could not change the decreased production of the pro-inflammatory cytokines IL8, IL6 and TNFα." (PMID 36389723, 2022).